POMC (proopiomelanocortin)
Diseases named in the same sentence as POMC in open-access papers (continued):
Sharing a sentence is not in itself a finding about the gene and the disease.
Obesity (continued). "Phase III studies on this drug to treat rare causes of obesity, such as POMC deficiency, leptin receptor mutation, Prader-Willi syndrome, Bardet-Biedl Syndrome, and Alström syndrome, are currently under way." (PMID 36767008, 2023). "This receptor was found to be associated with obesity and hepatic steatosis through its regulation of pro-opiomelanocortin (POMC) expression." (PMID 38098473, 2023). "Obesity is a common risk factor for numerous health conditions and POMC deficiency has been shown to be associated with the development of this disease." (PMID 37036864, 2023). "POMC mutation-driven obesity is a recessive genetic disease characterized by hyperphagia and excessive body weight." (PMID 37152279, 2023). "Setmelanotide was initially FDA-approved in 2020 for chronic weight management in individuals six years or older with obesity caused by POMC deficiency, proprotein subtilisin/kexin type 1 (PCSK1), or LEPR deficiency." (PMID 37937009, 2023). "Decreased activity in POMC cells has been shown to be associated with increased food intake and obesity and has been demonstrated in the offspring of obese mothers." (PMID 36969815, 2023). "We demonstrate that chronic inhibition of arcuate neurons expressing proopiomelanocortin (POMC) or paraventricular hypothalamic neurons expressing melanocortin receptor 4 (MC4R) causes massive obesity." (PMID 37069175, 2023). "MC4R's appetite-reducing effect, secondary to the promotion of satiety and energy use, makes it an ideal therapeutic target; setmelanotide is especially beneficial for individuals with obesity related to POMC or MSH deficiency." (PMID 37937009, 2023). "Deficiency of this receptor or its polymorphism leads to increased food intake and obesity through dysregulation of the proopiomelanocortin (POMC)-containing neurons." (PMID 37664841, 2023). "Mutations/polymorphisms in the POMC gene are associated with early onset of obesity and adrenal insufficiency." (PMID 37511900, 2023). "Setmelanotide is an effective medication for the disease of obesity in patients older than 6 years if the patient has POMC deficiency, PCSK1 deficiency, LEPR deficiency, or Bardet–Biedl syndrome." (PMID 37835041, 2023). "Other causes of monogenic obesity, such as POMC (proopiomelanocortin) gene mutations or leptin gene mutations, are much rarer." (PMID 37629396, 2023). "Conversely, pathogenic mutations affecting POMC can result in genetically related severe obesity and MetS with pediatric onset." (PMID 37512517, 2023). "The hypothalamus through regulation of the pro-opiomelanocortin (POMC) gene controls energy homeostasis, and methylation in the POMC gene was found to be significantly associated with obesity." (PMID 37861729, 2023). "We also detected eight genetic variants affecting POMC (3.4%) that have been implicated in the development of obesity." (PMID 37835041, 2023). "Studies have consistently found higher levels of malonylation in the cartilage of obese mice fed a high-fat diet or with obesity induced by pro-opiomelanocortin (POMC) deficiency." (PMID 36818560, 2023). "Setmelanotide is under consideration for other rare genetic disorders associated with obesity including Bardet–Biedl syndrome, Alstrom syndrome, POMC, and other MC4R pathway heterozygous deficiency obesities." (PMID 36232301, 2022). "Hypothalamic IKK/NF-κB activation in response to dietary obesity induces neurodegeneration and inhibits neurogenesis, affecting neuronal phenotypes associated with energy balance, including the anorexigenic proopiomelanocortin (POMC) neurons." (PMID 35112705, 2022). "Obesity caused by mutations in POMC gene shows autosomal recessive inheritance, whereas those in MC4R are autosomal dominant." (PMID 36452324, 2022). "POMC neuron-specific disruptions of many genes have been reported to cause obesity or diet-induced obesity, specifically in female mice, but not in males." (PMID 36120438, 2022).
Obesity (continued). "Recent rat model studies indicate that rats deficient in the POMC gene develop obesity, glucose intolerance, and insulin resistance." (PMID 36012526, 2022). "The obesity phenotype in POMC mutation carriers resulting in β-MSH deficiency (Tyr5Cys, Tyr221Cys, and Arg236Gly) implies a significant effect of β-MSH on body weight, underscoring the importance of β-MSH as a physiologically relevant melanocortin ligand." (PMID 36291616, 2022). "In mice, POMCCre-dependent over-activation of the phosphatidylinositol-3-kinase (PI3K)-Akt-mammalian target of rapamycin (mTOR) pathway causes hyperpolarization of POMC neurons leading to obesity." (PMID 35490865, 2022). "Mice with loss of function of GABAB receptors from POMC neurons developed modest diet-induced obesity and glucose intolerance specifically in male mice." (PMID 36120438, 2022). "The phenotype of obesity was observed in POMC-deficient human patients, mice, and Labrador Retriever dogs." (PMID 35937837, 2022). "The new drug, Setmelanotide, is an eight-amino acid cyclic peptide labeled as BIM-22493 or RM-493 that functions as an MC4R agonist to treat the monogenic causes of obesity caused by POMC deficiency by lowering food intake and restoring insulin sensitivity." (PMID 36012526, 2022). "Functional loss of several key genes, including Lep, LepR and POMC, causes severe obesity in humans." (PMID 36676030, 2022). "Cilium depletion in hypothalamic pro-opiomelanocortin (POMC) neurons triggers obesity and insulin resistance in mice, the same phenotype as mice deficient in autophagy in POMC neurons." (PMID 35902579, 2022). "Enhanced PIP3 signaling in pro-opiomelanocortin (POMC) neurons causes a KATP channel activation that leads to diet-sensitive obesity." (PMID 36501104, 2022). "Setmelanotide was first approved in November 2020 by the U.S. FDA (USA) and is a novel medication for treating obesity caused by POMC and LEPR deficiency." (PMID 36009013, 2022). "Baseline IWQOL-Lite total scores suggest that some adults with severe obesity due to POMC or LEPR deficiency experience a lower QOL than individuals with general obesity." (PMID 35123544, 2022). "In fact, POMC neurons are considered to protect against obesity, so their loss compromises body weight regulation." (PMID 35603807, 2022). "The baseline characteristics of patients who enrolled in these two Phase 3 trials suggest that individuals living with rare genetic diseases of obesity, such as POMC or LEPR deficiency, have an impaired, and in some cases severely impaired, QOL." (PMID 35123544, 2022). "We present a unique case of 2 siblings exhibiting primary hypocortisolism with high levels of ACTH, obesity, and hyperphagia, in the presence of a novel homozygous POMC variant located within the PC2 cleavage site." (PMID 35737586, 2022). "The US Food and Drug Administration approved the drug for chronic weight management in patients 6 years and older with obesity caused by POMC, PCSK1, and LEPR deficiency." (PMID 36232301, 2022). "Since the first report in 1998, variants of the pro-opiomelanocortin (POMC) gene (MIM [609734]) have been found several times as a cause for human obesity." (PMID 35737586, 2022). "To summarize, this is the first report of patients with a variant in the KKRRP motif of the POMC gene, who had high ACTH levels, hyperphagia, and obesity." (PMID 35737586, 2022). "Further supporting the importance of POMC neuron 5‐HT2CR in energy homeostasis, a study showed that deficiency of 5‐HT2CR in the POMC neurons leads to insulin resistance, hyperphagia, hyperinsulinemia, obesity, hyperglycemia, and hyperglucagonemia." (PMID 35023323, 2022). "Two pivotal Phase 3 trials explored the effect of setmelanotide on body weight and hunger in individuals with obesity due to POMC (NCT02896192) or LEPR (NCT03287960) deficiency." (PMID 35123544, 2022). "Patients with POMC deficiency or Pomc knockout mice have severe metabolic disorders such as obesity and hyperphagia." (PMID 33826123, 2022).
Obesity (continued). "The POMC neurons and associated leptin–melanocortin pathway is currently a mainstay of obesity-based genetic research." (PMID 36012526, 2022). "Biallelic variants in the POMC gene can cause severe early-onset obesity, hyperphagia, red hair, and hypopigmentation, and a deficiency in adrenocorticotropin (ACTH)." (PMID 35737586, 2022). "Clinical studies in patients with obesity have revealed that mutations in leptin, pro-opiomelanocortin (POMC), and melanocortin 4 receptor (MC4R) are positively associated with hyperphagia, hyperinsulinemia, and excessive adiposity." (PMID 35757435, 2022). "POMC ablation is associated with obesity in humans and rodents, highlighting impaired POMC processing as a prime potential mediator of PC1/3-related obesity." (PMID 35963866, 2022). "Antipsychotic-induced weight gain/obesity is also associated with several neuropeptides or hormones that regulate energy balance and neuroendocrine function such as proopiomelanocortin (POMC), NPY, AgRP, insulin, leptin, and ghrelin." (PMID 36188456, 2022). "When mutating Ncoa1 in POMC neurons in mice, Pomc expression decreased, which led to hyperphagia, increased fat mass and diet-induced obesity." (PMID 33826123, 2022). "This synthetic peptide was approved by FDA at the end of 2020 for treating obesity caused by genetic defects in pro-opiomelanocortin (POMC), leptin receptor (LEPR), or proprotein convertase subtilisin/kexin type 1 (PCSK1)." (PMID 36291616, 2022). "A different study evaluated knockout effects of the mitoribosome protein CR6-interacting factor 1(Crif1) in POMC neurons, and found it causes neuronal mitochondrial stress and obesity in mice." (PMID 39871928, 2022). "The FDA approved setmelanotide in November 2020 for the treatment of obesity in patients with POMC, PCSK1 or LEPR deficiency." (PMID 34815532, 2022). "Proopiomelanocortin (POMC) deficiency is an extremely rare inherited autosomal recessive disorder characterized by severe obesity, adrenal insufficiency, skin hypopigmentation, and red hair." (PMID 34177811, 2021). "More recently, another example of the β-MSH implication in the maintenance of energy homeostasis in mammals was reported, describing a frameshift mutation in the coding sequence of the canine POMC gene leading to obesity." (PMID 33434184, 2021). "Deleting Mfn2 from murine satiety-promoting pro-opiomelanocortin (POMC)-producing neurons of mice led to extreme obesity, which was associated with mitochondrial morphological changes, including fewer MFN2-dependent MERCs." (PMID 34114603, 2021). "By lowering FoxO1 acetylation and protein levels, SIRT1 prevents obesity caused by the insulin-unsusceptible vital nuclear location of FoxO1 in pro-opiomelanocortin (POMC) neurons in male mice." (PMID 33804729, 2021). "Previously, we showed that rapid regulation of hypothalamic POMC following the introduction of HFD is an important factor determining predisposition to obesity." (PMID 34465367, 2021). "The activation of the POMC neuronal UPRmt was associated with a shift from glucose metabolism to fatty acid metabolism and protection against obesity by stimulating UPRmt and thermogenesis in white adipose tissue." (PMID 33917812, 2021). "Ablation of POMC neurons and loss of POMC-derived neurotransmitters lead to obesity, underscoring the importance of POMC neurons in regulation of energy homeostasis." (PMID 34603036, 2021). "It was recently reported in a model using Labrador retriever dogs that a 14-bp deletion in the gene encoding pro-POMC in these canines is associated with obesity." (PMID 34440144, 2021). "Previous studies showed that disrupted glucose sensing in POMC neurons caused the development of type 2 diabetes in mice with HFD-induced obesity." (PMID 33919440, 2021). "All POMC deficient patients had early onset obesity and adrenal insufficiency, the latter being the first diagnosis to be established." (PMID 34177811, 2021).
Obesity (continued). "Setmelanotide is used as replacement therapy for POMC deficiency to treat obesity in genetically severe obesity disorders involving impaired POMC neuronal function." (PMID 34066399, 2021). "In 2020, the FDA approved setmelanotide for chronic weight management in obese patients from six years onwards whose obesity is caused by POMC, LEPR, and proprotein convertase subtilisin/kexin type 1 deficiency (PCSK1)." (PMID 34066399, 2021). "Like CBP deficiency, HIF1α knockout in POMC neurons led to hyperphagia and obesity, likely due to decreased glycolytic activity and malonyl-CoA synthesis." (PMID 33917812, 2021). "In fact, novel mutations (Phe144Leu and Arg145Cys) located in the α-MSH domain of the POMC gene were observed to be associated with early-onset obesity." (PMID 34440144, 2021). "The genetic impairment of Sirt1 in POMC neurons causes hypersensitivity to diet-induced obesity due to reduced energy expenditure and compromises the remodelling of white adipose tissue." (PMID 33573212, 2021). "Similar to d‐fenfluramine, 5‐HT2CRs and POMC are implicated in the obesity therapeutic effect of sibutramine." (PMID 33909316, 2021). "Obesity caused by other genetic mutations in the leptin-melanocortin pathway include proopiomelanocortin (POMC) and melanocortin receptor 4 (MC4R), brain-derived neurotrophic factor (BDNF), and the tyrosine kinase receptor B (NTRK2) genes." (PMID 33511092, 2020). "Other studies have shown that ablation or inactivation of arcuate POMC neurons as well as genetic deficiency in POMC cause hyperphagia and obesity." (PMID 33253166, 2020). "Disruption of cilia formation specific to the synapsin 1- or POMC-expressing neurons also causes obesity albeit to a lesser degree, indicating the contribution of neuronal cilia in obesity development." (PMID 33188191, 2020). "The extent to which heterozygous mutations/CNV in PCSK1 and POMC are involved in monogenic obesity remains a point of discussion." (PMID 32384097, 2020). "Knock-in mice carrying a loss-of-function variant (NCOA1L1376P) identified in human obese patients show lower POMC gene expression, impaired leptin-induced depolarization of POMC neurons, increased food intake, and increased susceptibility to obesity." (PMID 32449767, 2020). "Socs3 mRNA levels in the arcuate are increased after prolonged high fat diet exposure, while Socs3 deficiency or specific deletion of Socs3 in POMC neurons leads to enhanced leptin sensitivity and resistance to diet induced obesity." (PMID 33382813, 2020). "Selective ablation of Mfn2 from POMC neurons in mice (POMCMfn2KO) caused leptin resistance, hyperphagia, and a reduction in energy expenditure and obesity." (PMID 33240218, 2020). "Dominant mutations in the proopiomelanocortin gene (POMC) are reported to cause severe, early-onset obesity in affected patients, often with other neuroendocrine features consistent with the diverse physiological roles of the multiple POMC-derived peptides." (PMID 33233816, 2020). "Hypothalamic POMC deficiency leads to obesity and metabolic deficiencies, largely due to the loss of melanocortin peptides." (PMID 30957016, 2019). "Several other animal studies have implicated altered POMC methylation in obesity‐related metabolic disease development." (PMID 31660128, 2019). "In a recent study investigating the long‐term impact of maternal HFD on offspring susceptibility to developing obesity, POMC methylation was investigated at weaning and after 20 weeks of exposure to either a low‐fat diet (LFD) or HFD." (PMID 31660128, 2019). "Intriguingly, congenital loss of primary cilia from POMC neurons also results in hyperphagia and obesity." (PMID 31249512, 2019). "For example, the sexually differentiated increase in inhibitory EC tone at SF-1/POMC synapses seen with diet-induced obesity/insulin resistance is linked to reduced PI3K/Akt signaling in male but not female animals." (PMID 30755252, 2019).
Obesity (continued). "In this study, a novel heterozygous POMC variant (p.Y160H) was described in a patient with early-onset, severe obesity whose obese mother was also affected by the same variant." (PMID 30991789, 2019). "Homozygous loss-of-function mutations in POMC have been reported to be very rare and a cause of severe obesity, ACTH deficiency and hypopigmentation in mice and humans." (PMID 30991789, 2019). "Because POMC deficiency causes severe obesity, tremendous efforts have been made to understand a causative role of the POMC neurons in the pathophysiology of both syndromic and diet-induced obesity." (PMID 29528284, 2018). "We next investigated how Sel1L deficiency in POMC neurons leads to age-associated obesity, first by measuring food intake and metabolic rates of Sel1LPOMC mice." (PMID 29457782, 2018). "Taken together, these data demonstrate that Sel1L deficiency in POMC neurons leads to age-associated obesity due to overeating, partially due to impaired leptin response at a step downstream of pY-STAT3." (PMID 29457782, 2018). "To explore the clinical implications of these findings, we investigated the interaction between Sel1L-Hrd1 ERAD and POMC-C28F, a disease-associated mutant identified recently in patients with early onset obesity." (PMID 29457782, 2018). "POMC neuron–specific Sel1L-KO (Sel1Lfl/fl POMC, hereafter referred to as Sel1LPOMC) mice develop hyperphagia and age-associated obesity even on a low-fat diet (LFD), with intracellular retention of POMC." (PMID 29457782, 2018). "Mice with POMC neuron–specific Sel1L deficiency developed age-associated obesity due, at least in part, to the ER retention of POMC that led to hyperphagia." (PMID 29457782, 2018). "When leptin central signalling is disrupted by genetic modifications, NPY expression increases and POMC expression decreases, putting the organism into an anabolic state, and increasing the risk of obesity." (PMID 30241328, 2018). "In line with this fact, inactivation of leptin receptor or dephosphorylation of STAT3 in POMC neurons reduces energy expenditure and increased food intake, thereby causing obesity in db/db mice." (PMID 29979770, 2018). "Consistent with this idea, human and mice studies showed that deletion of POMC neurons or their peptide product as well as MC4R deficiency results in obesity." (PMID 29997323, 2018). "In humans, the obesity phenotype reported is associated with mutations in the human prohormone convertase 1 gene and increased levels of unprocessed POMC." (PMID 29459251, 2018). "Two recent studies of the role of the UPR sensor IRE1α in POMC neurons showed mixed results in terms of susceptibility to diet-induced obesity." (PMID 29457782, 2018). "Proopiomelanocortin (POMC) deficiency is an extremely rare disorder characterized by early-onset obesity, adrenal insufficiency, red hair and decreased skin pigmentation." (PMID 28739551, 2018). "When the UPR sensor Ire1α is deleted in POMC neurons, mice are susceptible to diet-induced obesity, with reduced energy expenditure." (PMID 29457782, 2018). "We found that POMC deficiency leads to glucose intolerance and insulin resistance in female mice before the onset of obesity or hyperphagia." (PMID 30283405, 2018). "We have previously shown that hypothalamic POMC deficiency leads both to obesity and type 2 diabetes." (PMID 30283405, 2018). "Here, we report a surprising finding that ERAD involving the Sel1L-Hrd1 protein complex is required for POMC maturation in the ER, which, when defective, upregulates food intake, leading to age-associated obesity as a result of intracellular retention of POMC." (PMID 29457782, 2018). "Regarding the functions of miRNAs in the POMC neurons, it has been demonstrated that specific deletion of Dicer in POMC-expressing cells leads to obesity and diabetes which is associated with loss of POMC neurons in the ARC." (PMID 28424580, 2017).